MTOR (mechanistic target of rapamycin kinase)
Diseases named in the same sentence as MTOR in open-access papers (continued):
Sharing a sentence is not in itself a finding about the gene and the disease.
tumor (continued). "CD47 interacts with several receptors and molecules, including TSP-1 and SIRPα, to activate downstream pathways such as Akt/mTOR, NF-κB, PI3K/Akt, RhoA/ROCK, and others, to regulate cellular processes such as tumor cell survival, invasion, angiogenesis, cell migration, and apoptosis." (PMID 38188674, 2023). "Furthermore, compared with the SHP-2WT + planted tumor group, the SHP-2MAC-KO + planted tumor group exhibited a significant increase in p-Tie2, p-PI3K, p-Akt, p-mTOR, VEGF, COX-2, MMP2, and MMP9 in the liver tissue." (PMID 37304233, 2023). "mTOR-mediated control of STAT3 and NF-κB activities promotes an Immune-suppressive microglial phenotype that impedes the proliferation, infiltration, and immunological responses of effector T cells, thus facilitating tumor immune escape and growth." (PMID 37700840, 2023). "Furthermore, mTOR inhibitors in combination with CDK4/6 inhibitors resulted in a greater reduction of cell proliferation and tumor growth." (PMID 36792625, 2023). "Furthermore, tumor cells recruit more M2-like macrophages by releasing CCL2, and these macrophages promote gefitinib resistance by activating the AKT/mTOR pathway." (PMID 37649478, 2023). "PRS was composed of a tumor matrix targeting peptide of palmitic-K(palmitic)CREKA, Rapamycin (mTOR inhibitor), and SBC-115076 (PCSK9 inhibitor), which could self-assemble into a uniform nanomedicine with good stability." (PMID 37896137, 2023). "Based on mTOR activity alterations (Rictor overexpression or increased RICTOR CNV, without validated amplification), many of these tumour types have been identified by others as potential mTOR inhibitor targets." (PMID 37949943, 2023). "The results of the present study showed that after CRC liver metastasis, the SHP-2MAC-KO + planted tumor group obtained significantly higher levels of p-Tie2, p-PI3K, p-Akt, p-mTOR, VEGF, COX-2, MMP2, MMP9 in the liver tissue than the SHP-2WT + planted tumor group." (PMID 37304233, 2023). "Our data suggest that RB could repress PI3K/AKT/mTOR signaling pathway and autophagy to block the CXCL12 expression in CAFs, thereby weakening the CXCL12-mediated EC tumor progression." (PMID 37029408, 2023). "Several critical signaling pathways, such as phosphatidylinositol 3-kinase (PI3K)/protein kinase B (PKB, Akt)/mammalian target of rapamycin (mTOR), epidermal growth factor receptor (EGFR), and Ras, can regulate SREBP1/2 activation to mediate tumor growth and progression." (PMID 37568579, 2023). "The overexpression of MAPK4 has been reported to promote tumor progression via noncanonical activation of AKT/mTOR signaling." (PMID 36797541, 2023). "For example, in patients with metastatic renal cell cancer treated with an mTOR inhibitor everolimus, the 2-week relative changes of 18F-FDG uptake (SUVmax) from baseline were predictive of the 8-week change in tumor size as evaluated by conventional computed tomography." (PMID 36849435, 2023). "As the main channel for TEMs to promote tumor micro-angiogenesis and tumor immunosuppressive microenvironment, the PI3K/Akt/mTOR pathway plays a role in controlling such biological processes as cell proliferation, differentiation, migration, apoptosis, and adhesion." (PMID 37304233, 2023). "In addition, reverse-phase protein assay data from 7,663 TCGA patient samples from 31 tumor types demonstrated that p-4EBP1 and mTOR activity, but not p-S6K activity, was associated with poor prognosis, indicating the importance of 4EBP1 dysregulation in tumor progression." (PMID 37909334, 2023). "High expression levels of ABL1, FGFR2, MTOR, BRAF, and PARP1 were seen in both tumor subtypes." (PMID 36991316, 2023). "It has been demonstrated that the mTOR inhibitor rapamycin can activate the TGF-β receptor via a mechanism independent of TGF-β, while maintaining its inhibitory effect on mTOR, ultimately leading to the suppression of tumor cell proliferation." (PMID 36966336, 2023).
tumor (continued). "When other mTOR inhibitors, BEX235 or AZD8055, were combined with ABT-263 in vitro, a higher rate of apoptosis was observed, and either one of the mTOR combined inhibitors with navitoclax induced more tumor regression in xenograft models than the drugs alone." (PMID 36752780, 2023). "In these studies, suggest that miR-224-5p plays a significant role in the occurrence in HCC samples compared to adjacent tumor tissue samples, which is consistent with our findings that miR-224-5P was four times more abundant in HCC tissues with highly represented BCL2, MTOR, and GSK3B genes." (PMID 37168369, 2023). "Yet the molecular mechanisms that LncRNAs target the mTOR/S6K pathway on inducing tumor progression in HCC have not been clarified." (PMID 37160972, 2023). "The mammalian target of rapamycin (mTOR) is a protein kinase, part of the phosphoinositide 3-kinase (PI3K)-related kinase family, which plays a vital role in regulating protein synthesis and tumor progression." (PMID 37835416, 2023). "Interestingly, when LAMC2 was overexpressed by plasmid transfection on tumor cells with high LAMC2 expression, it had a beneficial effect on the biological behavior of OSCC through the PI3K/AKT/mTOR pathway." (PMID 37415741, 2023). "In addition, we also verified that overexpression of SELENBP1 inhibited the growth of tumor cells in vivo, and it was correlated with the inhibition of PI3K/AKT/mTOR pathway." (PMID 37606338, 2023). "With the promise of increased tumour efficacy of PARPi in combination with immunotherapies and other molecular targets, including the PI3K/AKT/mTOR pathway and other HR mechanisms seen in pre-clinical models, there are likely to be further biomarkers identified to aid more specific therapies." (PMID 36831687, 2023). "In summary, we discovered that mTOR regulates DNMT1 in a 4E-BP1-dependent manner to affect DNA methylation profiles, which emphasizes that dysregulation of oncogenic pathways can alter the epigenetic status to affect tumour growth." (PMID 37088830, 2023). "Furthermore, combined targeting of mTOR and DNMT1 has been demonstrated to have a more effective tumor suppressive function in HCC." (PMID 37088830, 2023). "Moreover, the Chou–Talalay algorithm uncovered that VitD/cisplatin combinations synergistically killed tumor cells (VitD < 100 nM) and also inhibited the PI3K/Akt/mTOR pathway." (PMID 36902107, 2023). "In addition, knockdown of the PI3K/AKT/mTOR pathway has been reported to prevent HCC cell proliferation and migration through inducing autophagy, suggesting the tumor suppressor roles of autophagy in liver." (PMID 36760166, 2023). "Tumor-negative adjacent cervical stroma cores were available for 30.0% (n = 18/60) of the p-mTOR-positive cohort for further analyses." (PMID 37623437, 2023). "In conclusion, SHP-2 in TEMs suppressed the activation or phosphorylated-Tie2 and consequently deactivated down-stream of PI3K-Akt-mTOR and resulted in the inhibited expression of angiogenic factor: VEGF, COX-2, MMPs, and eventually protect the tumor angiogenesis in CRC." (PMID 37304233, 2023). "The PI3K/Akt/mTOR and RAF/MEK/ERK pathways are involved in many human neoplasms." (PMID 37958702, 2023).
tumor (continued). "Moreover, many researchers have demonstrated that hnRNPA2B1 regulates tumor proliferation and metastasis through regulation of the AKT/mTOR signaling pathway." (PMID 37990246, 2023). "Concurrently, tumor-secreted chemokines recruit resident microglia in the brain, which undergo a transformation into a macrophage-like immune phenotype upon activation of multiple signaling pathways, including STAT3, NF-κB, mTOR, PI3K/Akt, and Wnt/β-catenin." (PMID 37700840, 2023). "Moreover, considering tumor heterogeneity and the small size of our population, looking for ESR1 mutations may not be sufficient, since other mutations, such as in the MAPK, PI3K/AKT/mTOR, and CDK4/6 pathways, have been demonstrated to be involved in the mechanisms of resistance." (PMID 36831647, 2023). "Furthermore, the phosphorylation of mTOR signalling and cell viability increased in RRAGC-mutant cells, as well as the tumour growth rate of RRAGC-mutant-harbouring animals." (PMID 37749558, 2023). "In conclusion, our work uncovers the phospholipid transporter PITPNC1 as a KRAS effector that controls central transcriptional and signalling nodes (i.e. MYC and mTOR) and unveils novel therapeutic strategies for KRAS-driven tumours in the context of a PITPNC1-regulated transcriptional network." (PMID 37210549, 2023). "Activation of chemokine receptors (CXCR1 and CXCR2) has pro-angiogenic and pro-inflammatory effects, inducing several signaling pathways, such as the protein kinase C, phospholipase C, PI3K/AKT/mTOR, RAS/RAF/MEK/ERK and NF-kB pathways, promoting tumor cell survival, proliferation, and dissemination." (PMID 37190141, 2023). "The triple-drug combination significantly (p < 0.0001) reduced the gene expression levels of VEGF, VEGFR, PI3K, PDK1, AKT1, mTOR and GSK3β while it significantly (p < 0.0001) enhanced the expression of PTEN, when compared with the tumor-control (TC) and other treatment groups." (PMID 37025487, 2023). "Salmonella directly infects the tumor cell and induce caspase 1 by inflammasomes and destroy them by apoptosis or regulating autophagy via AKT/mTOR pathway.Salmonella also mediates T cell and innate immune cell infiltration to tumor site which enhanced killing of Salmonella localized tumor." (PMID 38090593, 2023). "PI3K/AKT/mTOR pathway signaling was not statistically significantly altered in the post-PIKTOR tumor specimens across all patients in our differential gene and protein expression analyses." (PMID 37491309, 2023). "Importantly, specific subtypes is correlated with tumor immune infiltration and activation of PI3K/AKT/mTOR signaling pathway." (PMID 37152048, 2023). "On the other hand, among downregulated lncRNAs, LOC101928316 has been shown to induce higher GC cell proliferation, migration, and invasion in vitro, and greater tumor weight in vivo by promoting in some way the higher expression of AKT3, mTOR, and p-mTOR, and a lower expression of PTEN." (PMID 37047267, 2023). "Glycolysis in tumor cells as well as the downregulation of GLUT1 can limit T cell metabolism, which results in lower expression of mTOR, reduced expression of glycolysis-related genes, and decreased IFN-γ production, all of which contribute to the impairment of T cell’s antitumor abilities." (PMID 37342333, 2023). "A further mechanism analysis revealed that SLFN11 may inhibit the mTOR signaling pathway through RPS4X, while the mTOR pathway inhibitor INK128 could achieve a similar tumor suppression effect." (PMID 36672482, 2023). "PI3K/AKT/mTOR inhibitors can not only act on tumor cells but also work on immune cells and TME, which can improve the capacity of tumor immune surveillance, so combining ICIs and PI3K/AKT/mTOR inhibitors may promote the efficacy and reduce the resistance." (PMID 37345194, 2023). "Moreover, PWT33597 exhibited promising pharmacokinetic properties in multiple tumor xenograft models via an enduring reserve of PI3K and mTOR pathway signaling." (PMID 37046703, 2023).
tumor (continued). "To further assess the combined mTOR inhibition and BCL-XL degradation as a potential therapeutic strategy for BCL-XL and MCL-1 co-dependent SCLC, we first investigated the efficacy of DT2216 + AZD8055 combination using the H1048 xenograft tumor model." (PMID 36588105, 2023). "It targets AMPK (Adenosine monophosphate activated protein kinase) and mTOR (mammalian or mechanistic target of rapamycin) molecule signaling pathways by modulating NF-κB, MMP-2 (matrix metalloproteinase-2), and MMP-9 (matrix metallopeptidase 9) proteins to regulate tumor formation." (PMID 36677808, 2023). "The PI3K/AKT/mTOR pathway regulates GC cells’ function through various mechanisms, including promoting cell invasion, metastasis, epithelial-mesenchymal transition (EMT), angiogenesis, and activating tumor chemotherapy resistance." (PMID 38008753, 2023). "Moreover, due to the role of PAM and especially mTOR in metabolic regulation, PAM inhibition within nutrient-constrained tumor microenvironments can disrupt the balance between CD4 + /CD8 + T-cells, Tregs/T helper 17 (Th17) cells, and M1/M2 macrophages." (PMID 37596643, 2023). "Furthermore, we examined tumor tissues of mice treated with Co-Sp in vivo and found that phosphorylated levels of PI3K, Akt, and mTOR were lower in tissues of Co-Sp-treated tumors." (PMID 37313467, 2023). "PTEN, a tumor suppressor gene, plays an important role in many types of solid tumors by modulating cell apoptosis and cell cycle, and its suppressor activity depends on the activity of lipid phosphatase, which negatively modulates the PI3K/Akt/mTOR pathway." (PMID 37240338, 2023). "Understanding the critical role of the mTOR pathway in tumor growth has driven a growing number of PI3K/AKT/mTOR inhibitors that have not yet achieved significant clinical success." (PMID 38057772, 2023). "In addition, many studies have shown that TCM can also overcome drug resistance by regulating the tumor microenvironment, cell cycle, hypoxia, tumor stem cells, autophagy, key signaling pathways such as the PI3K/Akt/mTOR pathway, Hedgehog pathway, and others." (PMID 37469862, 2023). "We did not use the Akt inhibitors like GSK 690693 to confirm the PRAME overexpression-induced malignant behavior in the LSCC cell lines and primary tumor xenografts, contributing to enhance our hypothesis that PI3K/AKT/mTOR is involved in LSCC development." (PMID 36910848, 2023). "From the results, we noticed that tumor cells highly expressed AUP1 significantly correlated with proliferation marker (MCM2, MCM6), PI3K-AKT-MTOR pathway (Akt1, TSC1, mTOR, Foxo1), and autophagy signaling (Atg3, Atg4B, Atg4D, Atg7, Atg9A, Atg16L1) in IDH wildtype tumor cells." (PMID 37029364, 2023). "Moreover, tumor cells treated with piperine showed increased Bax and decreased Bcl-2 expression, whereas the expression of p-PI3K, p-Akt, and p-mTOR uniformly decreased." (PMID 37762259, 2023). "In different tumor types, the WNT pathway may activate mTOR signaling, while mTOR signaling may suppress the WNT/β-catenin pathway." (PMID 37176048, 2023). "Dying tumor cells could release MVs loaded with PD-L1 to suppress the function of T cells and induce M2 phenotype macrophages via TBK1/STAT6 and AKT/mTOR signals, contributing to the suppressive TIME." (PMID 36993986, 2023). "Since we observed increased phosphorylation of GSK3β at position Ser9, this, as well as the phosphorylation of Akt and mTOR already discussed, suggests an escape mechanism of the treated GBM cells, which ultimately promotes tumor cell survival even upon TMZ+AT101/AT101 therapy." (PMID 37240419, 2023). "Moreover, both in vitro and in vivo studies further confirmed that PRAME can facilitate the proliferation, migration, invasion, and EMT of LSCC cells and promote tumor growth, at least partially by activating PI3K/AKT/mTOR pathways." (PMID 36910848, 2023).
tumor (continued). "In addition to promoting tumor progression, macrophages promote endocrine resistance through, e.g., downregulation of ER and PR and activation of the PI3K/Akt/ mTOR pathway." (PMID 36996051, 2023). "Unlike antiangiogenic agents, mTOR mainly acts in tumor cells, where angiogenesis-related genes involved in binding to the immunophilin FK-binding protein are inhibited." (PMID 36703202, 2023). "In addition, the phosphorylation of the RPS6KA3 substrates (BAD S118, MTOR S1261, SRF S224, etc.), which involved in the regulation of cell differentiation and the inhibition of apoptotic were upregulated in tumor samples." (PMID 37704624, 2023). "This means that many signaling pathways are involved in regulating tumor growth, not just the mTOR signaling pathway." (PMID 37305384, 2023). "Likewise, the inhibition of catabolic pathways (IL-6, TNF-alpha), balanced with the stimulation of anabolic pathways (FoxO3a, p-AKT, p-mTOR, and P-GSK-3β), has occurred in the counteraction of tumor-induced cachexia." (PMID 38004420, 2023). "Our research suggests that the combination of mTOR inhibitors and KIF18B inhibitors may synergistically enhance their preventing recurrence and anti-tumor effect." (PMID 37957153, 2023). "Inhibitors of the PI3K/AKT/mTOR signaling pathway, such as dactolisib, have potential antineoplastic activity targeting tumor cell apoptosis and growth inhibition in PI3K/mTOR-overexpressing tumor cells." (PMID 37685932, 2023). "In summary, our study demonstrated that LHPP suppressed proliferation, migration, invasion and tumor formation of GC cells via regulation of the EMT in vitro, and the mechanism may be related to regulation of the PI3K/AKT/mTOR pathway." (PMID 36484014, 2022). "Activation of the PI3K/Akt/mTOR pathway is correlated with aggressive behaviour and poor prognosis of RCC tumours and is more significantly altered in ccRCC, high TNM stage tumours, and tumours with poor prognostic features." (PMID 36474188, 2022). "They showed that simultaneously targeting glycolysis and mTOR complexes directly with glucose analog 2-deoxyglucose (2-DG) and mTOR inhibitor AZD8055 reduced tumor growth significantly and provided a stronger effect in combination than either 2-DG or AZD8055 alone." (PMID 35573694, 2022). "Moreover, glutamine metabolism promotes the activation of several signaling pathways, such as the mammalian target of rapamycin (mTOR) and mitogen-activated protein kinase (MAPK) pathways, to support tumor cell growth and proliferation." (PMID 35625656, 2022). "Some studies have found that RIMKLB can affect reproductive function of mammals, and in tumor research, RIMKLB may coordinate with DDIT4 function to mediate mTOR inhibition and growth inhibition of tumor cells." (PMID 35444692, 2022). "In addition, CAP induced the autophagy and apoptosis of tumor cells through endoplasmic reticulum stress and the downregulation of the AKT/mTOR pathway." (PMID 36510333, 2022). "Therefore, in tumour tissues under hypoxic conditions, activation of the PI3K/Akt/mTOR pathway promoted the expression of Glut‐1 and HIF‐1α." (PMID 35415942, 2022). "Firstly, all available mTOR inhibitors have mostly a cytostatic but not cytotoxic effect on tumor cells." (PMID 36077374, 2022). "In addition, overexpression of miR-99a/b in HCC cells results in significant inhibition of tumor growth by suppressing the expression of IGF1R and MTOR." (PMID 35328346, 2022). "Moreover, miR-215-3p acts as a tumor suppressor in MM, inhibiting cell proliferation and promoting apoptosis in MM cells by targeting RUNX1 and deactivating the PI3K/AKT/mTOR pathway." (PMID 36466549, 2022).